LINC03097 (long independently transcribed non-coding RNA 3097)
Gene: Long non-coding RNA gene on chromosome 2 (206,640,073 to 206,641,282, forward strand). Ensembl gene ENSG00000231653.
Diseases named in the same sentence as LINC03097 in open-access papers:
LINC03097 is named in the same sentence as 1 disease in open-access papers, as found by Europe PMC text mining. Sharing a sentence is not in itself a finding about the gene and the disease. The quoted sentences say what the papers report.
fetal growth restriction (1 paper, 2025). A fetus that does not grow beyond the 10th percentile of conventionally accepted weight for gestational age. "Specifically, LINC03097 (ENST00000527727) appeared associated with fetal growth restriction (FGR), and H19 (ENST00000415029) with placenta accreta." (PMID 40870007, 2025).